MCM7 (minichromosome maintenance complex component 7)
Diseases named in the same sentence as MCM7 in open-access papers (continued):
Sharing a sentence is not in itself a finding about the gene and the disease.
bladder transitional cell carcinoma (1 paper, 2011). The most common morphologic subtype of urinary bladder carcinoma (over 90% of cases). "Quantitative real-time PCR analysis using 23 normal bladder tissues, 124 bladder transitional cell carcinomas (TCCs) and 12 upper urinary tract transitional cell carcinomas (UUT-TCCs) showed elevated mRNA levels of MCM7 in bladder and especially UUT-TCCs compared with normal bladder tissues." (PMID 21619671, 2011).
breast luminal cancer (1 paper, 2025). "Recently, it has been proposed that MCM7 gene expression could be a prognostic factor in breast luminal cancer." (PMID 40361484, 2025).
cervical dysplasia (1 paper, 2019). "In normal and benign hyperplastic cervical tissue, MCM7 expression is restricted to basal and immediate para-basal layers, while full thickness immunostaining is observed in high grade cervical dysplasia and invasive cancers." (PMID 31640696, 2019).
chronic atrophic gastritis (1 paper, 2023). Atrophic gastritis that is persistent and long-standing. "The elevated expression of MCM7 in both chronic atrophic gastritis and GC, as shown by our comprehensive investigation, suggests that this protein may serve as a promising biomarker for the early detection of GC." (PMID 37594635, 2023).
ciliopathy (1 paper, 2019). A genetic disorder of the cellular cilia or the cilia anchoring structures, the basal bodies, or of ciliary function. "Injection of a MO against Mcm7, which resulted in retention of intronic sequences and hence a premature stop codon rendered embryos with a ciliopathy-like phenotype, namely a distinct body curvature, pinheads, small eyes and pericardial edema." (PMID 30329080, 2019).
Cirrhosis (1 paper, 2025). A chronic disorder of the liver in which liver tissue becomes scarred and is partially replaced by regenerative nodules and fibrotic tissue resulting in loss of liver function. "To validate the clinical relevance of our findings, we analyzed cirrhotic human tissue samples and observed that both MCM7 mRNA and protein levels were significantly elevated in cirrhosis patients compared to healthy individuals." (PMID 40789837, 2025).
colorectal tumors (1 paper, 2017). "High levels of the helicase MCM7 and the polymerase theta POLQ in colorectal tumors were significantly linked to poor patient survival." (PMID 28161520, 2017).
dwarfism (1 paper, 2023). "Mutations in TRAIP were found in patients suffering from primodial dwarfism and the recombinant protein carrying the patient mutation (R18C) still forms short ubiquitin chains on MCM7 but fails to repair cisplatin-ICL repair while promoting TMP-ICL repair in Xenopus system." (PMID 36594163, 2023).
esophageal diseases (1 paper, 2016). "The significant increase of MCM4 and MCM7 expression compared with Ki-67 suggests that MCM4 and MCM7 are potentially more sensitive markers in differentiating various stages of esophageal disease progression." (PMID 27476776, 2016).
fibrosarcoma (1 paper, 2021). A malignant mesenchymal fibroblastic neoplasm affecting the soft tissue and bone. "Using Detwiller Sarcoma’s datasets, the results showed the overexpression of MCM7 in fibrosarcoma (fold change = 2.236) compared with normal samples." (PMID 34239894, 2021).
fibrosis (1 paper, 2025). the formation of excess fibrous connective tissue in an organ or tissue in a reparative or reactive process. "Hepatocyte-specific overexpression of MCM7 accelerates fibrosis progression, while its knockdown mitigates it in Schistosoma japonicum- and CCl4-induced fibrosis models." (PMID 40789837, 2025). "Moreover, increased MCM7 expression was found to positively correlate with the severity of hepatic fibrosis in both S. japonicum- and CCl4-induced murine fibrosis models." (PMID 40789837, 2025).
gastroesophageal reflux disease (1 paper, 2015). A chronic disorder characterized by reflux of the gastric and/or duodenal contents into the distal esophagus. "High CA9 expression may be related to the acidic environment caused by gastroesophageal reflux disease in the gastroesophageal junction and associated with tumorigenesis through BMI1, MCM4 and MCM7." (PMID 26156831, 2015).
head and neck cancer (1 paper, 2008). A primary or metastatic malignant neoplasm affecting the head and neck. "MCM7 and CDKN2A (p16) were proposed as biomarkers for HPV-positive head and neck cancer, while CDKN2A (p16) alone was suggested as a marker in HPV-infected oropharyngeal cancers with favourable prognosis." (PMID 18349847, 2008).
Hypercholesterolemia (1 paper, 2017). An increased concentration of cholesterol in the blood. "Simvastatin, an agent for hypercholesterolemia treatment, activated the MCM7/p-RB/γH2AX axis and induced DNA damage in TamR cells, especially when combined with tamoxifen." (PMID 28150753, 2017).
invasive carcinoma (1 paper, 2021). A carcinoma that is not confined to the epithelium, and has spread to the surrounding stroma. "MCM7 was detected within the invasive carcinoma region, although at a lower level than in areas of persistent infection with MmuPV1, whereas pS6 was upregulated in the representative invasive region near the invasive front but not within the upper epithelial layers." (PMID 34281391, 2021).
kidney cancer (1 paper, 2025). Primary or metastatic malignant neoplasm involving the kidney. "Based on these results, we conclude that MCM7 acts as a tumor-associated gene in kidney cancer." (PMID 40943553, 2025).
large-cell lung carcinoma (1 paper, 2021). "In this study, we found that MCM7 was highly expressed in LUAD, while MCM8/10 were overexpressed in large cell lung cancer and LUSC, all of which negatively associated with patient’s OS." (PMID 33936158, 2021). "Furthermore, MCM5 showed a high expression level with a fold change of 4.628 in LUSC samples in Bhattacharjee’s dataset, while MCM7 exhibiting an increased mRNA level in large-cell lung carcinoma with a fold change of 4.547 in Hou’s dataset." (PMID 33936158, 2021).
laryngeal carcinoma (1 paper, 2022). Carcinoma that arises from the laryngeal epithelium. "As assessed by MCM7 labeling index, the laryngeal cancers expressing PTHrP at nuclear level showed a higher proliferative activity than those expressing PTHrP in the cytoplasm." (PMID 35761298, 2022).
leiomyosarcoma (1 paper, 2021). An uncommon, aggressive malignant smooth muscle neoplasm, usually occurring in post-menopausal women. "Using Barretina Sarcoma’s datasets, the results showed that MCM7 was higher expressed in myxoid/round cell liposarcoma (fold change = 3.047), pleomorphic liposarcoma (fold change = 2.349), leiomyosarcoma (fold change = 2.288) and myxofibrosarcoma (fold change = 2.339) compared with normal samples." (PMID 34239894, 2021).
liver cirrhosis (1 paper, 2025). "In this study, we observed significant upregulation of MCM7 expression in hepatocytes in liver fibrosis models induced by Schistosoma japonicum and carbon tetrachloride (CCl4), as well as in patients with liver cirrhosis." (PMID 40789837, 2025). "Here, we show that minichromosome maintenance complex component 7 (MCM7) is predominantly upregulated in hepatocytes of liver fibrosis mouse models and in liver cirrhosis patients." (PMID 40789837, 2025). "Notably, we observed that MCM7 expression was also increased in both liver cirrhosis patients and two murine liver fibrosis models induced by S. japonicum infection and CCl4 treatment, respectively." (PMID 40789837, 2025). "Furthermore, in liver cirrhosis patients, a positive correlation was observed between the expression of MCM7 or SHCBP1 mRNA and increased IL11 expression." (PMID 40789837, 2025). "Our study identified a significant positive correlation between MCM7 and IL11 expression in patients with liver cirrhosis." (PMID 40789837, 2025).
liver fibrosis (1 paper, 2025). "Hepatocyte-specific MCM7 deficiency protected against liver fibrosis in a S. japonicum-and CCl4-induced mouse model." (PMID 40789837, 2025). "Our data indicate that targeting MCM7 or its associated signaling pathway may represent a promising therapeutic strategy for the treatment of liver fibrosis." (PMID 40789837, 2025). "While our observations in human tissue samples provide important context, the primary conclusions about MCM7’s role in liver fibrosis and its therapeutic potential are derived from extensive murine model studies." (PMID 40789837, 2025). "Given the critical role of MCM7 in liver fibrosis pathogenesis and its interaction with SHCBP1, we analyzed gene expression datasets (GSE61376, GSE25713, and GSE55747) and our RNA-seq data from S. japonicum- and CCl4-induced liver fibrosis models." (PMID 40789837, 2025). "Hematoxylin and eosin (H&E), Masson’s trichrome staining, and immunohistochemistry revealed that hepatocyte MCM7 knockdown in S. japonicum-induced mice significantly attenuated hepatic fibrosis compared to controls." (PMID 40789837, 2025). "To explore the potential role of MCM7 in liver fibrosis, we first analyzed MCM7 transcript levels in normal and fibrotic liver samples from both patients and murine models." (PMID 40789837, 2025). "Having confirmed the upregulation of MCM7 in liver fibrosis, we next aimed to identify potential extracellular activators of MCM7 gene transcription." (PMID 40789837, 2025). "Taken together, these results indicate that hepatocyte MCM7 overexpression aggravates liver fibrosis in both S. japonicum- and CCl4-induced mouse models." (PMID 40789837, 2025). "Our results demonstrated that rhIL11 treatment significantly alleviated histological injury, collagen deposition, liver fibrosis severity, and hydroxyproline content induced by MCM7 overexpression." (PMID 40789837, 2025). "This study initially demonstrates that dysregulated MCM7-mediated protein interactions serve as critical regulatory factors in liver fibrosis development." (PMID 40789837, 2025). "Our further studies demonstrated that MCM7 is predominantly expressed in hepatocytes during liver fibrosis." (PMID 40789837, 2025). "Data analysis showed that MCM7 mRNA expression was significantly upregulated in liver fibrosis tissues compared to normal tissues." (PMID 40789837, 2025). "In conclusion, our findings indicate that SHCBP1 is significantly upregulated in liver fibrosis and correlates with increased MCM7 expression." (PMID 40789837, 2025). "To investigate the mechanism by which hepatic MCM7 influences liver fibrosis pathogenesis, we performed immunoprecipitation using an anti-MCM7 antibody in a hepatocyte cell line." (PMID 40789837, 2025). "The activation of the YAP/TAZ pathway in liver fibrosis is well-documented, which explains the increased MCM7 expression observed in liver fibrosis." (PMID 40789837, 2025). "Collectively, these findings underscore the critical role of MCM7 in liver fibrosis and highlight its potential as a therapeutic target for treating this disease." (PMID 40789837, 2025). "To explore the potential impact of targeting MCM7 in hepatocytes on established liver fibrosis, we employed an adeno-associated virus serotype 8 (AAV8) vector to knockdown MCM7 in S. japonicum-induced liver fibrosis models." (PMID 40789837, 2025). "To explore whether YAP activation drives the increased expression of MCM7 in liver fibrosis, we treated primary hepatocytes and HepG2 cells with XMU-MP-1, an inhibitor of the Hippo signaling pathway." (PMID 40789837, 2025). "To explore whether MCM7 promotes liver fibrosis through IL11 in vivo, we administered rhIL11 to inhibit endogenous IL11 activity in mouse models subjected to S. japonicum infection or chronic CCl4 treatment." (PMID 40789837, 2025).
liver fibrosis (continued). "Additionally, recombinant human IL11 (rhIL11), which effectively inhibits endogenous IL11 signaling, significantly attenuated the exacerbation of liver fibrosis driven by MCM7 overexpression in vivo." (PMID 40789837, 2025). "In conclusion, our study underscores the pivotal role of MCM7 in liver fibrosis." (PMID 40789837, 2025). "Moreover, MCM7 knockdown in hepatocytes via an AAV8 vector inhibited the development of liver fibrosis, while MCM7 overexpression exacerbated fibrosis induced by S. japonicum and CCl4." (PMID 40789837, 2025). "Furthermore, in vivo experiments revealed that treatment with rhIL11 in MCM7-overexpressing mice substantially suppressed the progression of liver fibrosis." (PMID 40789837, 2025). "Overexpression of MCM7 in the liver exacerbated liver fibrosis." (PMID 40789837, 2025). "Additionally, the CCl4-induced liver fibrosis model, a widely used model, was employed to further investigate the role of hepatocyte MCM7 in liver fibrosis." (PMID 40789837, 2025). "Additionally, we found that increased hepatic SHCBP1 mRNA expression is significantly correlated with elevated MCM7 mRNA levels in liver fibrosis." (PMID 40789837, 2025). "However, the specific role of MCM7 in liver fibrosis remains unknown." (PMID 40789837, 2025). "In conclusion, our findings demonstrate that MCM7 enhances hepatocyte-derived IL11 production, which drives HSC activation and promotes liver fibrosis progression." (PMID 40789837, 2025). "Mechanistically, our findings demonstrated that MCM7 activates IL11 expression via the SHCBP1-RACGAP1-STAT3 signaling pathway, thereby promoting the hepatic stellate cell activation and driving liver fibrosis progression." (PMID 40789837, 2025). "This interaction between MCM7 and SHCBP1 regulates IL11 expression through the RACGAP1-STAT3 pathway, underscoring a novel mechanism for liver fibrosis progression." (PMID 40789837, 2025). "We further utilized AAV8 vectors to drive MCM7 overexpression (AAV-MCM7), thereby generating hepatocyte-specific MCM7 overexpression in S. japonicum-induced liver fibrosis mice." (PMID 40789837, 2025). "The involvement of MCM7 in this regulatory pathway unveils a novel mechanism by which MCM7 modulates IL11 expression, a process that may critically influence liver fibrosis progression and potentially other pathological conditions." (PMID 40789837, 2025). "Given that hepatic MCM7 activates IL11 transcription and IL11 promotes HSC activation, we hypothesized that MCM7 accelerates liver fibrosis by inducing IL11 release, which subsequently activates HSCs." (PMID 40789837, 2025). "Additionally, further analysis revealed a positive correlation between MCM7 expression and STAT3 phosphorylation in murine liver fibrosis models." (PMID 40789837, 2025).
nasopharyngeal carcinoma (1 paper, 2022). A carcinoma arising from the nasopharyngeal epithelium. "MCM7 was an independent prognostic factor for survival outcomes in nasopharyngeal cancer and may be a potential therapeutic target for treatment." (PMID 34144903, 2022).
oral cancer (1 paper, 2017). "The genes CTNNB1 and MCM7 have been well studied for oral cancer but were not present in the databases which were taken initially for this study." (PMID 28559546, 2017).
pancreatitis (1 paper, 2015). Inflammation of the pancreas. "In addition, specific TFs, including minichromosome maintenance complex component 7 (Mcm7); lymphoid-specific helicase (Hells); and minichromosome maintenance complex component 6 (Mcm6), that function in the unwinding of DNA were identified to participate in Mist1KO pancreatitis." (PMID 25975747, 2015).
penile cancer (1 paper, 2019). A primary or metastatic malignant neoplasm that affects the penis. "In humans, MCM7 expression is also seen in HPV-negative penile cancers, suggesting that MCM7 expression may depend on the amount of proliferating cells within the lesions and not entirely on the papillomaviral oncoproteins E6 and E7." (PMID 31640696, 2019).
pituitary tumor (1 paper, 2017). A benign or malignant neoplasm affecting the pituitary gland. "In conclusion, our findings demonstrate for the first time that both MCM7 and miRNAs within the miR-106b~25 cluster (miR-25-3p, miR-93-3p, miR-93-5p and miR-106b-5p) are co-expressed in pituitary tumors and are associated with their invasive character as well as unfavorable outcome after resection." (PMID 28432562, 2017).
prostatic intraepithelial neoplasia (1 paper, 2011). "The miR-106b∼25 cluster cooperates with its host gene MCM7 in cellular transformation both in vitro and in vivo, so that the concomitant overexpression of MCM7 and the miRNA cluster triggers prostatic intraepithelial neoplasia in transgenic mice." (PMID 21339820, 2011).
rectal adenocarcinoma (1 paper, 2020). "MCM7 was 2.380- and 2.176-fold higher in the colon and rectal adenocarcinoma samples in that order compared with contrastingly relevant normal tissues." (PMID 32597491, 2020).
renal carcinoma (1 paper, 2025). A carcinoma arising from the epithelium of the renal parenchyma or the renal pelvis. "Given the fact that all factors from the MCM7-miR-106b-25 locus are overexpressed in ccRCC, we set out to evaluate if they cooperate in processes associated with renal cancer progression." (PMID 40943553, 2025). "Functional studies in RCC-derived cell lines were conducted to evaluate the effects of miRNAs on target gene expression, as well as MCM7, and the combined contributions of MCM7 and the miR-106b-25 cluster to renal cancer progression." (PMID 40943553, 2025). "MCM7 is upregulated in renal cancer at the mRNA and protein levels, and its dysregulation contributes to cell proliferation and caspase-3/7 activity." (PMID 40943553, 2025). "In this study, we demonstrate that MCM7 expression is upregulated in renal cancer and affects cell proliferation and caspase-3/7 activity, contributing to RCC progression." (PMID 40943553, 2025). "Based on our findings, we conclude that elevated MCM7 and miR-106b-25 expression contribute to renal cancer progression." (PMID 40943553, 2025). "Further studies are needed to elucidate the functional impact of the altered expression of the MCM7-miR-106b-25 axis in renal cancer." (PMID 40943553, 2025). "Taken together, our findings support an important role for MCM7 and the miR-106b-25 cluster in renal cancer." (PMID 40943553, 2025). "To study the consequences of upregulated levels of MCM7 in cancer progression, we silenced MCM7 expression in renal cancer cells, Caki-2 (Figure A1), and analyzed the effect on cell behavior." (PMID 40943553, 2025). "In conclusion, our study demonstrates that MCM7 mRNA and protein levels are upregulated in renal cancer." (PMID 40943553, 2025). "We observed that MCM7 silencing attenuated the caspase-3/7 activity in both renal cancer cell models–Caki-2 and KIJ-265T." (PMID 40943553, 2025).
renal cell carcinoma (1 paper, 2025). "In this work, we aimed to explore the consequences of dysregulated levels of MCM7 and the hosted miR-106b-25 cluster on the progression of Renal Cell Carcinoma." (PMID 40943553, 2025).
retinoblastoma (1 paper, 2021). A malignant tumor that originates in the nuclear layer of the retina. "Previous study reported that curcumin decreased the cell viability and altered the cell cycle of retinoblastoma cells by downregulating MCM7." (PMID 34299042, 2021).
Shwachman-Bodian-Diamond Syndrome (1 paper, 2023). "In particular, MCM2 (minichromosome maintenance complex 2), MCM5, MCM7, multiple copies in T-cell lymphoma-1, RPS25 ribosomal protein S25, and Shwachman-Bodian-Diamond Syndrome were successfully confirmed." (PMID 37391046, 2023).
skin squamous cell carcinoma (1 paper, 2021). A carcinoma arising from the squamous cells of the epidermis. "MCM7 was significantly correlated with tumorigenesis, progression, malignant conversion, and prognosis in skin squamous cell carcinoma." (PMID 34490114, 2021).
Tetralogy of Fallot (1 paper, 2016). A congenital cardiac malformation comprising pulmonary stenosis, overriding aorta, ventricular septum defect, and right ventricular hypertrophy. "Pnn, Spcs1, Ddx39, Mcm7 and Phkb mRNAs were downregulated in HLHS patient RVs when compared to control RVs obtained from Tetralogy of Fallot patients (black bar vs white bar)." (PMID 27485310, 2016).